TNF (tumor necrosis factor)
Diseases named in the same sentence as TNF in open-access papers (continued):
Sharing a sentence is not in itself a finding about the gene and the disease.
Cognitive impairment (continued). "Blood studies showed that higher levels of pro-inflammatory markers were linked with a more severe motor phenotype (IFN-γ, TNF-α, IL-2, and IL-10), faster motor progression (CRP and IL-6), cognitive impairment (IFN-γ, TNF-α, IL-2, and IL-10), and worse sleep quality (CRP)." (PMID 36337703, 2022). "Our results show that CLP-induced hippocampus-dependent cognitive deficits were accompanied with increased HIF 1a and decreased BNIP3L, increased protein levels of TNF-α, IL-6, and IL-β, and damage to mitochondrial structures and neuronal apoptosis in the hippocampus." (PMID 36569834, 2022). "In addition, AASWE improved learning and memory function of LPS-induced cognitive deficits with the inhibition of oxidative stress, activation of the cholinergic system and regulation of pro-inflammatory mediators (p-JNK, p-NF-κB, TNF-α, and IL-6)." (PMID 33046678, 2021). "HIV-1 Tat protein exerts proinflammatory effects on microglia, astrocytes and neurons that produce key pro-inflammatory cytokines, such as tumor necrosis factor-alpha (TNF-α) and interleukin-1 beta (IL-1β), which ultimately lead to neuron damage and cognitive deficits." (PMID 34358137, 2021). "Developing drugs to modulate the production of TNFα, such as NF-κB, P38 MAPK, and TNF receptor antagonist inhibitors, may be potential candidates for the treatment of cognitive impairment, AD, and other neurodegenerative diseases." (PMID 33574879, 2021). "However, oral administration of NK210, NK219, or Mx decreased cognitive impairment-like behaviors, NF-κB+/Iba1+ cell population, and IFN-γ and TNF-α expression in the hippocampus, while BDNF+/NeuN+ cell population and IL-10 expression increased." (PMID 34667205, 2021). "Finally, patients with PD and cognitive deficit (MMSE < 26) (n = 51) exhibited significantly increased plasma EV pro-IL-1β, IL-6, TNF-α, and IL-10 levels and a significantly decreased TGF-β1 level." (PMID 33803292, 2021). "The hippocampus-dependent cognitive decline induced by chronic neuronal inflammation can be significantly reversed when using TNF-α synthesis inhibitors, suggesting that TNF-α is an important mediator of neuronal dysfunction and cognitive impairment triggered by chronic neuroinflammation." (PMID 34540188, 2021). "Intriguingly, our results show that 8 days after surgery animals that received Bup present cognitive deficits and no altered levels of hippocampal TNF-α, while animals treated with Par-150 mg/kg have no cognitive deficit but increased hippocampal TNF-α." (PMID 33980934, 2021). "It is well established that inflammatory responses, including activation of glial cells and production of inflammatory cytokines such as IL-1β, IL-6, COX-2, iNOS, and TNF-α, induced by CCH could further result in neuronal cell death and cognitive deficits." (PMID 31900229, 2020). "Peripheral administration of etanercept counteracts Aβ-induced memory impairment and attenuates hippocampal levels of TNF in a non-transgenic mouse model of amyloid induced cognitive deficits." (PMID 33343293, 2020). "Notably, a strong correlation is present in Down syndrome cases showing preclinical AD among the plasma TNF-α increase, a deficit in NGF maturation (with grown concentrations of proNGF), and an increased degree of cognitive impairment." (PMID 32296418, 2020). "INF‐λ and TNF‐α levels were higher, as was nitric oxide production, in AD patients in mild and severe stages compared with patients in earlier phases (moderate stage and mild cognitive impairment), indicating progressive increases in INF‐λ and TNF‐α in human AD patients." (PMID 32857910, 2020). "TNF-α production appears to be upstream of microgliosis in the context of ZIKV infection, and is insufficient to cause cognitive impairment in the absence of microglial activation." (PMID 31488835, 2019).
Cognitive impairment (continued). "In summary, the negative correlation of FC with the level of IL-6, TNF-alpha and ammonia strengthens the role of systemic inflammation and hyperammonemia in the pathogenesis of cognitive impairment among cirrhotic patients with CHE55." (PMID 31036843, 2019). "Going beyond previous work, the present study took a novel methodological approach by examining the mediation of systemic inflammation (i.e., serum levels of IL-6, TNF-α and CRP) on age-related cognitive impairments (i.e., deficits in processing speed and short-term memory)." (PMID 30127734, 2018). "Several biomarkers were also highlighted as potential biomarkers of GDM-related cognitive impairment such as AGEs, serine-phosphorylated IRS-1 and inflammatory markers such as tumor necrosis factor α (TNF-α), high-sensitivity C-reactive protein (hs-CRP), leptin, interleukin 1β (IL-1β), and IL-6." (PMID 30563117, 2018). "TNF-α crosses the BBB by receptor-mediated endocytosis to induce microglial activation, leading to further TNF-α release, increased production of NO, mitochondrial dysfunction, neuronal death, and consequent cognitive impairment." (PMID 30100992, 2018). "Furthermore, Icariside II also possibly suppressed neuroinflammation by reducing expression of IL-1, IL-1β, TNF-α, COX-2, and iNOS mRNA and protein, which eventually reversed Aβ-induced cognitive deficits." (PMID 30424767, 2018). "Previous studies also showed that HHcy may result in neuroinflammation as indicated by elevated levels of IL1β, TNFα and IL6 in mice brain tissue, and these inflammatory mediators were all shown to independently result in cognitive impairments." (PMID 30425189, 2018). "Elevated baseline TNF-α has also been associated with lower hippocampal volume and with greater likelihood of mild cognitive impairment (MCI) patient conversion to AD suggesting increased systemic TNF-α may have roles in hippocampal neurodegeneration." (PMID 27633985, 2017). "Additionally, heat stress can cause glial activation with NF-κB pathway in the hippocampus, which subsequently led to the upregulation of TNF-α, IL-1β, iNOS and COX-2, resulting in neurodegeneration and cognitive impairment." (PMID 28946610, 2017). "Together, these gene expression results along with the trending lower levels of TNFα in fasting plasma do not support a role of either Aβ clearing or increased inflammation in the hippocampus as the mechanism for cognitive impairment in NEXLPL+/- mice." (PMID 26263173, 2015). "Taken together, our data suggest that heat stress might induce activation of NF-kB, which subsequently leads to the elevation of TNF-α and IL-1β, and the up-regulation of iNOS and COX-2, resulting in cognitive deficits in mice." (PMID 26001832, 2015). "Studies from our laboratory showed that Hemodialysis (HD) patients without cognitive deficit show an increase in TNF-α serum levels." (PMID 25961830, 2015). "During the past few years, an increasing amount of evidence has supported the view that the excessive release of proinflammatory cytokines, including tumor necrosis factor (TNF)-α, interleukin (IL)-1β and IL-6, is involved in cognitive impairment after surgery and anesthesia." (PMID 23613842, 2013). "We, and others, have previously demonstrated that TNFα produced from HIV-1 infected or activated macrophage and microglia in the CNS is a major player in HIV-1-induced neuroinflammation, that eventually leads to neuron damage and cognitive impairment." (PMID 21494611, 2011). "The levels of cortisol and proinflammatory cytokines such as TNFα in the serum of MDD patients with adult stressors increased compared with healthy controls, and were alleviated by SSRIs treatment, accompanied by improvement in depressive symptoms, anxiety symptoms and cognitive impairments." (PMID 40303307, 2025).
Cognitive impairment (continued). "Our results demonstrated that T3 treatment reversed cognitive impairment and increased Akt and GSK3 phosphorylation in the treated group, while also reducing microglial activation (Iba-1) and GFAP expression (reactive astrocytes), along with TNF-α, IL-6, and IL-1β levels in the hippocampus." (PMID 39513900, 2024). "Previous studies have shown that IL-1β, but not TNF-α or IL-6, is the exclusive cytokine within the CNS that has been verified to remain elevated for up to 70 days in rats survived neonatal sepsis but subsequently developed cognitive impairment." (PMID 38665289, 2024). "(I)PD patients who developed cognitive impairment during the study had higher CSF levels of TNF-alpha at baseline compared to patients without the development of cognitive impairment and compared to patients who presented with cognitive impairment already at baseline." (PMID 36906614, 2023). "Cognitive impairment was not correlated with TNF-α at any time point (all P>0.05)." (PMID 37878890, 2023). "In our study, the mean values of TNFα and hsCRP in U3A students did not exceed the reference values, which may indicate that the subjects do not have cognitive impairment." (PMID 33808526, 2021). "In conclusion, NK210, Lactobacillus sp, and NK219, Bifidobacterium additively or synergistically control IFN-γ to IL-10 and TNF-α to IL-10 expression ratios in the host with and without immune imbalance, resulting in the alleviation of gut dysbiosis, inflammation, and cognitive impairment." (PMID 34667205, 2021). "There is a positive correlation between peripheral TNF-α levels and negative symptom severity, as well as a negative correlation with positive symptoms in all populations, general psychopathology in AChR, and cognitive deficits." (PMID 34501305, 2021). "However, the highly toxic effect of IL-6 may overweight the potential compensatory effect of TNF-α and INF-γ, leading to cognitive impairment eventually." (PMID 24884485, 2014). "However, the lack of correlation between MMP-2 and TNF-α and cognitive function in our study was intriguing and suggests that the cognitive deficits in TRS and CMS may not be mediated by a single mechanism." (PMID 38429778, 2024). "Similarly, although the neuroanatomy and molecular mechanisms of sickness-induced hypoactivity remain poorly understood both indomethacin and the COX-1 inhibitor sc-560 reduced measures of LPS-induced sickness behavior and cognitive deficits without effect on systemic or central TNF-α." (PMID 27633985, 2017). "Recombinant CXCL13 induced cognitive deficits and increased the expression of phospho-ERK as well as IL-1β and TNF-α in hippocampus of wild-type mice, but not CXCR5−/− mice." (PMID 33161894, 2020). "Although TNF‐α antagonism has shown promise in reducing depressive symptoms in chronic inflammatory diseases, there is currently a lack of direct studies exploring the impact of TNF‐α on cognitive impairment in MDD." (PMID 39236111, 2024). "These evidences suggested that IL-6 might be a more appropriate marker for cognition impairment, such as the MHE in the current study Although literature has shown an increased serum level of TNF-α in cirrhotic patients with HE, we did not detect such a phenomenon in the current study." (PMID 26039496, 2015).
heart failure (611 papers, 2007 to 2026). Inability of the heart to pump blood at an adequate rate to meet tissue metabolic requirements. "Compared with heart failure-associated transudative ascites, malignant ascites demonstrated higher levels of TNF-α, IL-6, IL-10, IL-12p70, IL-18, IL-23, s4-1BB, and TGF-β1, while albumin levels were lower." (PMID 42193466, 2026). "Elevated CRP levels have been strongly associated with an increased risk of heart failure, while IL-6 and TNF-α have been implicated in the progression of ventricular dysfunction." (PMID 40787514, 2025). "Heart failure is associated with the induction of pro-inflammatory cytokines, of which IL-6 and TNF-α are commonly used inflammatory factors." (PMID 40951892, 2025). "Elevated pro - inflammatory cytokines like TNF - α and IL - 6 among RA patients have been linked to heart failure pathogenesis, emphasizing the interaction between systemic inflammation and cardiovascular dysfunction." (PMID 40313943, 2025). "The review further examines various inflammatory biomarkers that have been implicated in heart failure, such as cytokines (including TNF-α and IL-1) and C-reactive protein (CRP)." (PMID 40710370, 2025). "No previous studies have observed early changes in cardiac macrophage subpopulations in heart failure with preserved ejection fraction, which is associated with an early and transient increase in circulating pro-inflammatory TNF-α levels." (PMID 41155489, 2025). "TNF-α exacerbates cardiac failure by upsetting the homeostasis-preserving mechanism, causing dysfunction and inhibiting anti-inflammatory reactions." (PMID 40458758, 2025). "In naturally occurring heart failure in humans, elevated circulating TNF-α concentrations have been associated with increased CVD mortality." (PMID 41284707, 2025). "The proinflammatory response is a hallmark of heart failure, and the overproduction of inflammatory factors (e.g., TNF-α and interleukin-6 (IL-6)) can induce mitochondrial DNA damage, inhibit antioxidant factors and promote ROS generation." (PMID 40507126, 2025). "Secondly, TNF-α can promote the progression of heart failure by mediating oxidative stress causing cardiomyocyte hypertrophy, apoptosis, and fibrosis." (PMID 41179565, 2025). "The literature suggests that TNF inhibitors can cause AEs, including cancer, serious infections, heart failure, and demyelinating disorders, such as multiple sclerosis and lupus-like syndrome, after administration in predisposed individuals." (PMID 38335182, 2024). "Supporting thisdata, a high expression of cytokines such as tumor necrosis factor-alpha (TNF-α),caspase-9, interleukins 1 beta (IL-1β), and IL-6 in the heart and serum of LVADcandidates are associated with the severity of heart failure." (PMID 39484122, 2024). "Further investigation also revealed that the risk factors for heart failure include pulmonary hypertension, aortic valve or coronary artery involvement, onset age >38 years, and serum tumor necrosis factor (TNF)-α concentration >10 pg/ml." (PMID 37416916, 2023). "Having anemia, cachexia, and nutritional deficiencies usually results in the elevation of tumor necrosis factor-alpha along with different pro-inflammatory cytokines known to be a result of chronic kidney disease and heart failure (HF)." (PMID 37529809, 2023). "TNF-α was the only other biomarker associated with risk for subsequent heart failure hospitalization." (PMID 36896709, 2023). "Elevated levels of IL-6 or TNF are associated with an increased risk of cardiovascular events and a worse prognosis in patients with heart failure." (PMID 37047011, 2023). "Increased expression of TNF-α has been associated with decreased myocardial contractile function and worse outcome in heart failure participants, whereas higher levels of IL-8 are associated lower risk of myocardial ischemia." (PMID 36399460, 2022).
heart failure (continued). "TNF is an important proinflammatory cytokine that causes heart failure by suppressing the body's natural anti-inflammatory responses and disrupting the homeostatic system." (PMID 35813433, 2022). "TNF-α and IL-6 are implicated in the pathophysiology of heart failure and of pulmonary hypertension." (PMID 35307783, 2022). "In IBD patients with stable class III-IV NYHA heart failure, anti-TNFα therapy was associated with increased odds of decompensation and acute heart failure exacerbations." (PMID 36289474, 2022). "High levels of TNFα have been detected in the plasma of humans and mice following myocardial infarction (MI), which is a major underlying cause of heart failure worldwide." (PMID 35883637, 2022). "In a German biologics register, TNF-α inhibitors (etanercept, infliximab, or adalimumab) were shown to be more likely to be beneficial than harmful with regard to the risk of heart failure in patient with RA." (PMID 35844550, 2022). "In line, high doses of infliximab, a chimeric monoclonal antibody to TNF-α, increased the combined risk of death from any cause or hospitalization for heart failure (hazard ratio = 2.84) in patients with moderate-to-severe heart failure." (PMID 34674004, 2022). "More importantly, ‘inflammaging’ has been suggested as a major risk factor for the development of heart failure in geriatric patients following hip fracture and has been mostly linked to elevated systemic levels of IL-6 and TNF." (PMID 36131923, 2022). "The exception is salivary TNF-α, which, with an AUC close to unity, differentiates HF patients by severity of heart failure symptoms according to the New York Heart Association classification." (PMID 36300113, 2022). "Anti-TNF-α therapy failed in clinical trials and was even associated with a deterioration of heart failure in patients who were mainly diagnosed with ischaemic cardiomyopathy." (PMID 35844550, 2022). "TNF is a well-known mediator of inflammation-associated heart failure, which induces systolic dysfunction." (PMID 34439792, 2021). "TNF-α inhibitors exhibited consistent benefits in reducing the risks of MI, heart failure, CV death, all-cause mortality, and 3P-MACE." (PMID 34504395, 2021). "The study showed that patients with heart failure (HF) have increased levels of some inflammatory markers, among which TNF-α is the most prominent and linked with the progression and severity of the disease." (PMID 33671607, 2021). "Irrefutably, increased levels of TNFα in the stress state has been linked to the pathophysiology of heart failure development in various clinical investigations and animal models." (PMID 34966735, 2021). "The present study also revealed that inflammation-related cytokines (IL-6, TNF-α and adiponectin) were associated with heart failure severity." (PMID 34685378, 2021). "Several pro-inflammatory cytokines, including tumor necrosis factor-alpha (TNF-alpha), interferon-gamma, interleukin-1-beta, interleukin-6, interleukin-17, and interleukin-18 have been implicated in the pathogenesis of heart failure." (PMID 33391898, 2021). "Higher levels of inflammation-related cytokines (IL-6, TNF-α, adiponectin) are associated with heart failure severity and predict poor clinical outcomes." (PMID 34685378, 2021). "Elevated concentrations of circulating TNFα are linked with increased susceptibility to heart failure and impaired glucose and lipid homeostasis and this also contributes to atherosclerotic plaque thickening." (PMID 34502180, 2021). "In fact, heart failure patients show also elevated cardiac TNF-α levels associated with dynamic changes in TNFR1 and TNFR2 expression." (PMID 33053859, 2020). "On the contrary, Tnfrsf1b (gene encoding TNFR2) genetic deficiency exacerbated heart failure and increased the lethality of TNF-α overexpressing mice pointing to the cardioprotective role of TNFR2." (PMID 33053859, 2020).